CD4 (CD4 molecule)
Diseases named in the same sentence as CD4 in open-access papers (continued):
Sharing a sentence is not in itself a finding about the gene and the disease.
severe combined immunodeficiency (continued). "However, when CD4 T cells are adoptively transferred into SCID (severe combined immunodeficiency) mice that lack functional T and B cells, CD4 T cells are no longer sufficient for protection, and depletion of CD4 T cells during SARS-CoV infection coincided with a reduction in antibody production." (PMID 26965109, 2016). "Classically, ZAP70-related combined immunodeficiency is characterized by normal CD3+ counts, normal or elevated CD4+T cells, and markedly reduced or absent CD8+ T-cells (0–2% of total T cells)." (PMID 40901120, 2025). "In immunodeficient mice (nude, T cell depleted and severe combined immunodeficiency [SCID] mice), characterised by an absence of CD4+ T-lymphocytes and egg antibodies responses, praziquantel is inefficient in treating the S. mansoni infection." (PMID 25671125, 2014). "However, unlike in combined immunodeficiency (CID), CD8+, CD4+, and CD45RA+ naive T cell numbers were generally normal or even increased." (PMID 30941118, 2019). "Its importance has been demonstrated by the observation that Zap70-deficiency in humans results in a Severe Combined Immunodeficiency (SCID) characterized by the absence of CD8+ T cells and in a defective activation of the CD4+ T-cell compartment." (PMID 28415650, 2017).
brucellosis (42 papers, 2008 to 2026). Brucellosis is a bacterial infection that spreads from animals to people via unpasteurized dairy products or by exposure to contaminated animal products or infected animals. "Multiple immune cell lineages (e.g., CD4+ T, DCs, monocytes) were associated with specific brucellosis disease stages, that is, DCs, monocytes and CD4+ T cells were significantly associated with acute, sub‐acute and chronic patients, respectively." (PMID 39135683, 2024). "After brucellosis vaccination in cattle, CD4+ T-cells have been implicated as the main source of IFN-ɣ, whereas CD8+ T-cells which were proliferating differentiate into cytotoxic effectors cells." (PMID 26352261, 2015). "Murine brucellosis is markedly exacerbated in β2-microglobulin knockout mice that lack CD8+ T cells compared to CD4+ T cell deficient mice or C57BL/6 (wild type) mice, illustrating the predominant role of MHC class I-restricted T cells in controlling Brucella infection." (PMID 22558103, 2012). "Based on the results from CIBERSORT, we identified a significant increase in the abundance of CD8 + T cells and NK cells in patients with brucellosis compared to the normal control group, while the abundance of B cells and CD4 + T cells was lower." (PMID 40996975, 2025). "Compared to the control group, the proportion of CD8 + T cells and NK cells was higher in patients with brucellosis, while the proportion of B cells and CD4 + T cells was lower." (PMID 40996975, 2025). "CD8 + T cells and NK cells were higher in brucellosis than in the control group, whereas B cells and CD4 + T cells were lower, which was confirmed by flow cytometry." (PMID 40996975, 2025). "Next, to further identify NB-related miRNAs, a GSE107554 dataset comprising peripheral blood CD4 T cell samples from brucellosis patients and healthy controls was utilized as a validation cohort." (PMID 40626048, 2025). "Analysis using CIBERSORT and flow cytometry indicated that the abundance of CD8 + T cells and NK cells is significantly higher in patients with brucellosis compared to healthy controls, while the abundance of B cells and CD4 + T cells is lower." (PMID 40996975, 2025). "The reduction in CD4 + T cells, a primary defense source, reaffirms the notion that protection against brucellosis relies on CD4 + T cells." (PMID 40996975, 2025). "Similar to our findings in apoptosis, significant activation of cell migration pathways in CD4+ T cells was also observed in brucellosis patients, with high migration scores in CD4_eMemory, CD4_Treg, CD4_Th1, CD4_Th2 and CD4_Memory." (PMID 39135683, 2024). "Utilizing an apoptosis scoring system, we found that CD4+ T cells in brucellosis patients likely underwent apoptosis relative to healthy donors, consistent with previous findings that Brucella can induce apoptosis of human T lymphocytes." (PMID 39135683, 2024). "This is consistent with previous findings that the levels of CD3+CD4+ T lymphocytes in brucellosis patients were significantly reduced in comparison to healthy control." (PMID 39135683, 2024). "The MDSCs were isolated from chronic brucellosis patients and co-cultured with CD4+/CD8+ T cells from healthy controls at the ratio of 0:1, 1:1, 1:2 and 1:4 for 72 hours." (PMID 38352057, 2024). "In this study, we examined T cell function by co-culturing with MDSCs from peripheral blood of chronic brucellosis patients, showing that CD4+ and CD8+ T cell proliferation and their IFN-γ expression were largely inhibited by MDSCs (P<0.001)." (PMID 38352057, 2024). "This aligns with earlier reports which observed a significant decrease in CD3+CD4+ T lymphocyte levels in individuals with brucellosis when compared to healthy donors." (PMID 39135683, 2024). "At present, several flow cytometry methods based on intracellular CD4+ IFN-γ+ T assays have been developed to identify bovine brucellosis and avoid false-positive serum reactions." (PMID 37376677, 2023).
brucellosis (continued). "The cytokine levels and the CD4+/CD8+ ratio pattern can serve as indicators of the immune status in brucellosis." (PMID 38139181, 2023). "A Meta-analysis showed a significant decrease of CD4/CD8 ratio in brucellosis-infected patients, compared to healthy subjects." (PMID 35681174, 2022). "Protection against brucellosis is long believed to be CD4+ T cell-dependent and less on CD8+ T cells." (PMID 36263034, 2022). "In a murine model of brucellosis, IL-10− knockout mice showed reduced bacterial loads in the spleen, and early IL-10 production by CD4+ CD25+ T cells prevented the immune activation of macrophages and promoted persistent intracellular infection." (PMID 34592958, 2021). "This contrasts with RB51-induced immunity where CD4+ T cells were the primary source of defense, and reaffirms the notion of CD4+ T cell-dependence for protection to brucellosis." (PMID 31951645, 2020). "CD8+ T cells were assumed to be less important for protection against brucellosis than CD4+ T cells, and CD8+ T cell immunity was thought to be limited to cytotoxicity." (PMID 31951645, 2020). "In the 4 studies we selected, each of them reported significantly decreased CD4+/CD8+ ratio in human brucellosis patients compared to control individuals." (PMID 29888294, 2018). "Some studies reported that the CD4+ T lymphocyte proliferation reaction ability in patients with chronic brucellosis was significantly lower than that of the healthy controls and the acute patients." (PMID 29888294, 2018). "This is the first study of miRNA expression that analyses human CD4+ T cells to clarify the mechanism of chronicity in brucellosis." (PMID 29897958, 2018). "Results of the meta-analysis showed a significantly decreased proportion of CD4+/CD8+ ratio human brucellosis patients compared to healthy individuals ([MD = −0.6291, 95% CI (−0.99, −0.27), p = 0.0006])." (PMID 29888294, 2018). "The present study investigated immunological factors and their roles in the transition of brucellosis from an acute to a chronic infection in CD4+ T cells." (PMID 29897958, 2018). "Changes of peripheral blood CD4+ T cells were reported by 8 trials, containing 396 patients with human brucellosis and 212 cases of healthy control." (PMID 29888294, 2018). "Results of the meta-analysis showed a significantly decreased proportion of CD4+ T cells in human brucellosis patients compared to healthy subject individuals ([MD = −9.03, 95% CI (−12.93; −5.14), p < 0.0001])." (PMID 29888294, 2018). "The pooled analysis presented a significant decrease of the CD4+/CD8+ ratio in human brucellosis patients compared to healthy subjects." (PMID 29888294, 2018). "Meta-analysis showed a significantly decreased proportion of CD4+ T cells in human brucellosis patients compared to healthy subject individuals." (PMID 29888294, 2018). "This is also depicted by the significantly higher number of CD4+ lymphocytes in the BM at early stages of infection, which in brucellosis correlates with Th1 polarization." (PMID 30622977, 2018). "Of the 8 included trials, 4 articles provided data of the changes of peripheral blood CD4+/CD8+ ratio in human brucellosis patients compared to controls including 291 patients with human brucellosis and 141 cases of healthy control." (PMID 29888294, 2018). "In a murine model, IL-10 has been shown to influence the development of brucellosis by downregulating the response of CD4+ T helper cells and the secretion of IFN-γ." (PMID 29343543, 2018). "In chronic brucellosis, immunosuppressive state establishes with the concomitant increase of CD4+, CD25+ T cells in spleen, which ultimately plays a significant role in the regulation of effector T lymphocytes." (PMID 27014640, 2016). "After intraperitoneal infection, it has been shown that CD4+CD25+ T cells produce IL-10 during acute brucellosis that favor bacterial persistence in mice." (PMID 28018318, 2016).
brucellosis (continued). "In humans, IFN-γ producing CD4+ T cells, CD8+ T cells and γδ T cells have been implicated in the control of brucellosis." (PMID 24367519, 2013). "Previous studies with CD4+ T cells, however, have shown that the CD4+ T cell is the major producer of IFN-γ in brucellosis." (PMID 24288554, 2013). "The protection against brucellosis that is conferred by CD4+ T-cells is primarily through secretion of relevant cytokines that stimulate other immunocytes to eliminate Brucella." (PMID 23533646, 2013). "A number of studies have demonstrated a role for either CD4+ or CD8+ T cells in the control of brucellosis." (PMID 22194770, 2012). "CD4+ T cells are the major producers of IFN-γ in brucellosis, although other subsets such as CD8+ T cells also contribute." (PMID 22194770, 2012). "Itcould be assumed that in chronic relapsing brucellosis patients prior exposuresto Brucella LPS, as a result of relapses during the chronic stage, leads to “crosstolerance” (low percentage of CD4+/CD28+ T-cells) to further in vitro E.coli LPS challenge." (PMID 19190764, 2008). "We then performed the transcriptome analysis of CD4+ T cells in brucellosis patients." (PMID 39135683, 2024). "Among CD4+ T‐cell subsets, Th1 cells have a fundamental role in conferring an effective immune response against brucellosis, and increased frequencies of this subset (CD4_Th1) were observed in acute and sub‐acute brucellosis patients, consistent with a previous report." (PMID 39135683, 2024). "As a subset of CD4+ T cells, Th1 and Th2 cells also play an important role in brucellosis." (PMID 35659087, 2022). "Evidence of Tregs acting as suppressors of the T cell response to brucellosis was initially obtained from murine models, in which CD4+ CD25+ Tregs increased in the spleen of BALB/c mice and the antibody-mediated depletion of murine CD25+ T cells induced Brucella elimination from target organs." (PMID 34592958, 2021). "It would also be of interest to learn how CD4+ TRM cells are induced subsequent vaccination to brucellosis to determine, if these could then, confer protection." (PMID 31951645, 2020). "Brucellosis mouse model inoculated with T lymphocytes could reduce the number of brucella in mice spleen, which indicates that CD4+ and CD8+ T lymphocyte immunity is involved in resistance to brucella infection." (PMID 29888294, 2018). "Good candidate vaccines should be able to induce a complex immune response mainly characterized by proinflammatory pattern, cytotoxic CD8+ T-cells and Th1 and Th17 CD4+ T-cells, but also by some anti-inflammatory profile (IL-10), as demonstrated by the proved brucellosis vaccines." (PMID 26352261, 2015). "CD4+ T-cells are definitely the main source of IFN-ɣ following brucellosis vaccination in cattle." (PMID 26352261, 2015). "Interestingly, previous studies have demonstrated elevated numbers of CD4+CD25+ T cells in PBMCs from human patients with acute brucellosis as well as in draining lymph nodes from B. melitensis infected sheep." (PMID 23818855, 2013). "Indeed, Svetić and collaborators have suggested a possible role for CD4+ T cells in IL-10 production during acute murine Brucellosis." (PMID 23818855, 2013). "The higherpercentage of CD4+CD25+ T-cells inacute brucellosis could be attributedto the abundant milieu of proinflammatory cytokines observed in theacute disease." (PMID 19190764, 2008). "Thereduction of CD4+/CD25+ T-cells percentage after PHA plus E. coli cultureswas more pronounced in chronic relapsing brucellosis patients (CB1 subgroup),suggesting that relapses in brucellosis might be associated with disturbancesof IL-2/IL-2 receptor system." (PMID 19190764, 2008). "We also observed a similar CD4+/C8+ ratio pattern in the 3-AT-treated group in both Brucella-infected and non-infected mice, mirroring the patterns seen in patients receiving pre- and post-antibiotic treatment during acute brucellosis and in healthy individuals." (PMID 38139181, 2023).
brucellosis (continued). "While CD4+ T lymphocytes were long considered the most important source of IFN-γ in the response against brucellosis, several recent studies have indicated that CD8+ T lymphocytes may be equally or sometimes more important in mediating protection depending on the vaccine administered." (PMID 34335551, 2021). "Both CD8+ and CD4+ T cells respond specifically to B. abortus in mice, CD8+ T cells may function as specific cytotoxic cells in brucellosis caused by B. abortus, and one study indicated that immune modulation could result in an effective CD8+ T-cell role in secondary immunity." (PMID 24288554, 2013). "As shown in previous studies, the human immune system's defense against brucellosis depends on cellular immunity, which mainly affects antigen-presenting cells (APC), such as macrophages, dendritic cells, and CD4+ and CD8+ T cells." (PMID 34335092, 2021). "In vivo, IL-6, TNF-α, and CD80/CD86 are required for activation of the interferon gamma-producing CD4+ Th1 and CD8+ cytotoxic T cells, a protective response induced by the host against brucellosis." (PMID 34992597, 2021). "In vivo, IL-6, TNF-α, and CD80/CD86 are required in the activation of the interferon gamma-producing T CD4+ helper type 1 (Th1) and T CD8+ cytotoxic, a protective response induced by the host against brucellosis." (PMID 32765455, 2020). "To investigate changes in CD4+ and CD8+ T cell subsets in patients with acute brucellosis, we analyzed the following subsets in the blood: CD4 + IFN-γ + (Th1), CD4 + IL-4+ (Th2), CD8 + IFN-γ + (Tc1), and CD8 + IL-4+ (Tc2)." (PMID 32660627, 2020). "In brucellosis, peptides are presented by both MHC class-I and MHC class-II molecules and therefore, induce both CD4+ and CD8+Brucella-specific T cells." (PMID 33062939, 2020). "The results of this study show that the expressions of CD4+ and CD8+ T cells in patients at the acute stage are the highest, which are significantly higher than those in patients with chronic brucellosis." (PMID 31467933, 2019). "The expressions of PD-1 on CD4+ and CD8+ T cells in the acute brucellosis group were significantly higher than those in the chronic brucellosis group (P < 0.05)." (PMID 31467933, 2019). "The expressions of PD-1 on CD4+ and CD8+ T cells in the chronic brucellosis group were higher than those in convalescent patients and healthy controls (P < 0.05)." (PMID 31467933, 2019). "Further research is needed to confirm the changes of CD4+ and CD8+ T cell function in peripheral blood of patients with brucellosis." (PMID 29888294, 2018). "We have previously shown that heat-killed B. abortus (HKBA) can downregulate the PHA-induced increase of CD4+/CD25+ and CD14+/CD80+ cells of brucellosis patients." (PMID 19190764, 2008). "In a BALB/c mouse model of brucellosis, CD4 + CD25 + T regulatory cells may limit the effectiveness of CD4 + T cells and favor the maintenance and progression of B. abortus infection." (PMID 32660627, 2020). "The results showed that the frequency of CD4+ T lymphocytes and the ratio of CD4/CD8 cells in the peripheral blood of patients with brucellosis were significantly lower than those of healthy controls, and the frequency of CD8+ T lymphocytes was higher than that of healthy controls." (PMID 31467933, 2019). "There is immunologic dysfunction of T lymphocyte in patients with human brucellosis, the CD4+ and CD8+ T cells might be the important factors affecting the progress of brucellosis." (PMID 29888294, 2018). "The conclusions from different related researches of the changes in the percentage of CD4+ T, CD8+ T, and CD4+ T/CD8+ T ratios in peripheral blood in patients with brucellosis are not consistent." (PMID 29888294, 2018). "In brucellosis, adaptive immune response mechanisms are divided in three main steps: in the first step it inhibit the intracellular survival of Brucella, IFN-γ produced by CD4+, CD8+, and T cells which initiates the bactericidal function in macrophages." (PMID 27014640, 2016).
brucellosis (continued). "Furthermore, in all cases, Th1 CD4+ and CD8+ T-cell anti-brucellosis immune responses were elicited in immunized animals." (PMID 24716528, 2014). "Additionally, we identified T cells, more specifically CD4+CD25+ T cells, as the major source of this cytokine during acute brucellosis." (PMID 23818855, 2013). "IL-12 production by DCs is critical for driving a protective CD4 Th1 type immune response and the clearance of intracellular bacteria and triggers the production of IFN-γ, a pivotal cytokine involved in the control of murine brucellosis." (PMID 22927979, 2012). "Chronic brucellosis patients displaya defective Th1 response to PHA characterized by low-proliferation response ofCD4+ T-lymphocytes, diminished production of IL-2 and IFNγ, and low frequency of CD4+/CD25+ T-cellscompared to acute brucellosis patients." (PMID 19190764, 2008). "Moreover, a 5-fold greater number of IL-10 producing CD4+CD25+ T cells was detected at 9 d.p.i., compared to IL-10 producing CD4+CD25− T cells, suggesting that the CD4+CD25+ T cell subset is the major population responsible for IL-10 production during acute brucellosis in the mouse." (PMID 23818855, 2013). "Moreover, the significant induction of CD4+IFN-ɣ+ T-cells after S19 or RB51 vaccination and RB51 revaccination (RB51 group), as well as the absence of an IL-4 response, characterize the development of a predominant Th1 immune response following brucellosis vaccination in cattle." (PMID 26352261, 2015).